KL (klotho)
Diseases named in the same sentence as KL in open-access papers (continued):
Sharing a sentence is not in itself a finding about the gene and the disease.
Hypertension (continued). "Future large-scale prospective studies should include participants at higher risk to explore the relationships between the serum klotho concentration, blood pressure, hypertension, and arterial stiffness." (PMID 33504927, 2021). "A recent study on Klotho haplodeficient mice showed that Klotho deficiency led to arteriosclerosis and hypertension, but these effects were diminished by increasing SIRT1 activity." (PMID 34730891, 2021). "Recently, it was reported that the klotho expression levels in placenta is associated with preeclampsia, a disorder of pregnancy characterized by the onset of high blood pressure and early pregnancy loss in severe cases." (PMID 33413301, 2021). "Mice deficient in Klotho have been reported to develop salt-sensitive hypertension after high sodium challenge and a Klotho single nucleotide polymorphism with salt-sensitive hypertension has been described in adults with newly diagnosed hypertension." (PMID 32982966, 2020). "In humans, Klotho deficiency features medial calcification, intima hyperplasia, endothelial dysfunction, arterial stiffening, hypertension, impaired angiogenesis, and vasculogenesis (i.e., characteristics of early vascular aging)." (PMID 32982966, 2020). "This study provides the first evidence that stimulation of Klotho expression attenuates aging‐associated arterial stiffening and hypertension." (PMID 29659128, 2018). "The present study was carried out aiming to investigate the association of Klotho-rs564481 (C1818T) gene polymorphism with hypertension and CAD." (PMID 30547758, 2018). "A relationship between klotho and hypertension was suggested in a report that klotho polymorphisms are correlated with blood pressure levels." (PMID 30595559, 2018). "Our recent study showed that haplodeficiency of Klotho gene caused arterial stiffness and hypertension." (PMID 29659128, 2018). "In the Asian population, the Klotho C1818T gene polymorphism was associated with an increased risk of CADs, hypertension, glucose metabolism, and lipid levels." (PMID 30547758, 2018). "In conclusion, the findings of the present case-controlled study revealed the importance of genetic influences of Klotho polymorphism on hypertension and/or CAD susceptibility among the Iranian southeast population." (PMID 30547758, 2018). "In this content, the objective of this study was to investigate the possible association of the Klotho gene polymorphism with hypertension and CAD." (PMID 30547758, 2018). "Contrarily, it showed the association of Klotho gene polymorphisms with decreased risk of hypertension." (PMID 30547758, 2018). "New findings in the current study are consistent with these results in previous studies in demonstrating a significant correlation between klotho functional polymorphisms and the onset of cerebrovascular diseases in patients with hypertension." (PMID 30595559, 2018). "Actually, the klotho gene is first identified during the study on spontaneous hypertension, and klotho deficiency has close relationship with hypertension." (PMID 28929120, 2017). "After adjusting for relevant confounders, logistic regression analysis showed that the Klotho G-395A SNP was significantly associated with high blood pressure (OR 0.47, 95 % CI 0.31 to 0.71) and hypertriglyceridemia (OR 0.54, 95 % CI 0.31 to 0.98)." (PMID 26880028, 2016). "After adjusting for relevant confounders, logistic regression analysis showed that the Klotho G-395A SNP was significantly associated with high blood pressure (OR 0.47, 95 % CI 0.25 to 0.90) and low HDL-C (OR 0.69, 95 % CI 0.27 to 0.93)." (PMID 26880028, 2016). "After adjusting for relevant confounders, logistic regression analysis revealed that the Klotho G-395A SNP was significantly associated with high blood pressure (OR 0.48, 95 % CI 0.34 to 0.67) and hypertriglyceridemia (OR 0.66, 95 % CI 0.39 to 0.95)." (PMID 26880028, 2016).
Hypertension (continued). "Moreover, when administered with a selective SIRT1 activator known as SRT1720, arterial stiffness and hypertension were eliminated via Klotho loss in mice muscle cells KL+/−." (PMID 41567643, 2025). "In cases of Klotho deficiency, conditions such as atherosclerosis, hypertension, neovascularization disorders, cardiac fibrosis, sinoatrial node dysfunction, cardiac electrical activity disturbances, coronary heart disease, and inflammatory diseases may arise." (PMID 41517379, 2025). "Loss of Klotho thus results in increased aldosterone, sodium retention and hypertension." (PMID 41303567, 2025). "Also, deficiency of Klotho contributes to hypertension, arterial stiffening, endothelial dysfunction and many other age-associated disorders." (PMID 38213484, 2024). "Klotho deficiency is associated with various molecular consequences that collectively promote arterial stiffening, vascular aging, and endothelial dysfunction, all leading to the development of hypertension." (PMID 39616409, 2024). "In summary, among a nationally representative population of American adults, our study identified a significant association between dietary folate intake and serum Klotho levels, especially prominent in men, individuals aged 60 and above, and those with hypertension." (PMID 39040924, 2024). "Our results suggest that Klotho deficiency may create a vicious cycle with hypertension, potentially increasing CKD risk through mechanisms such as impaired endothelial function and activation of inflammatory pathways." (PMID 39777219, 2024). "This study aimed to determine the association of klotho protein with essential hypertension." (PMID 39616409, 2024). "Furthermore, recent research suggests that there is a connection between klotho deficiency and the development of essential hypertension." (PMID 39616409, 2024). "Therefore, the present study was designed to examine the association of klotho protein with essential hypertension and also to assess its direct and indirect effect on essential hypertension." (PMID 39616409, 2024). "The analysis revealed a significant decrease in klotho protein levels in cases compared to controls (1.52 ± 0.87 vs. 2.45 ± 0.90, P < 0.001), suggesting an inverse relationship of klotho protein with risk of essential hypertension." (PMID 39616409, 2024). "A point mutation in the human KL gene is related to hypertension and renal disease, suggesting that KL may be necessary to maintain normal renal function." (PMID 36794161, 2023). "Furthermore, a multivariate logistic regression analysis confirmed that participants with higher quartiles of serum Klotho concentration had a significantly reduced risk of postmenopausal hypertension compared to those in the lowest quartile." (PMID 37528365, 2023). "Serum Klotho concentration may serve as a valuable biomarker for risk stratification in postmenopausal women who are at risk of developing hypertension." (PMID 37528365, 2023). "The dose–response association demonstrated a trend of decreasing initially, followed by an increase and then another decrease in hypertension risk with an increase in Klotho concentration, characterized by a reflection point for serum Klotho concentration at 796.5 pg/ml (p for non-linearity 0.003)." (PMID 37528365, 2023). "Klotho-deficient mice exhibit stunted growth, renal disease, hyperphosphatemia, hypercalcemia, vascular calcification, cardiac hypertrophy, hypertension, organ fibrosis, multi-organ atrophy, osteopenia, pulmonary disease, cognitive impairment and short lifespan." (PMID 35903083, 2022). "According to the research, low circulating Klotho concentration may be a marker of mortality; however, the association between serum Klotho concentration and mortality in patients with hypertension is unclear." (PMID 36457804, 2022).
Hypertension (continued). "Our findings indicate that low serum Klotho concentration was substantially correlated with a greater risk of all-cause death, but not cardiovascular mortality in a nationwide representative sample of American individuals with hypertension." (PMID 36457804, 2022). "Therefore, we aimed to examine the association between serum Klotho concentration and all-cause and cardiovascular mortality in American patients with hypertension." (PMID 36457804, 2022). "Serum Klotho deficiency is also associated with hypertension in humans." (PMID 36457804, 2022). "Second, since the FGF23/Klotho axis is associated with hypertension and CVD, we were unable to determine whether the clinical impact of Klotho on mortality was reliant on or independent of FGF23." (PMID 36457804, 2022). "Interestingly, Klotho deficiency is associated with medial calcification, intima hyperplasia, endothelial dysfunction, arterial stiffening, hypertension, and impaired vasculogenesis." (PMID 34737707, 2021). "The deficiency of Klotho, predominantly expressed in the kidney and recognized as an aging-related molecule, could stimulate arterial stiffness and hypertension along with repressed aortic SIRT1 expression in mice." (PMID 33117155, 2020). "Activation of SIRT1 attenuates Klotho Deficiency-induced hypertension and arterial stiffness." (PMID 32509148, 2020). "The reason for this result may be that the sample size of our study may be small to indicate statistical significance and that other factors, such as hypertension, are more strongly associated with CMBs than Klotho." (PMID 31398214, 2019). "In previous studies, genetic variants of Klotho increased the risk of MS which could be related to their susceptibility to high fasting glucose, high blood pressure, hypertriglyceridemia, and decreased HDL cholesterol." (PMID 30943913, 2019). "The association of Klotho gene polymorphism with hypertension and CAD was assessed." (PMID 30547758, 2018). "In this study, we investigated whether compound H increases Klotho levels and attenuates aging‐associated arterial stiffening and hypertension." (PMID 29659128, 2018). "Moreover, the results of the present study are not consistent with the previous studies which indicated the association of Klotho gene polymorphisms with increased risk of hypertension." (PMID 30547758, 2018). "At the rs564481 locus, the Klotho C1818T gene polymorphism was associated with decreased risk of hypertension in all subjects category as well as a decreased risk of association with CAD combined with hypertension in those subjects older than 57 years." (PMID 30547758, 2018). "The association of the Klotho G-395A SNP with MetS could be linked to its observed influence on high blood pressure in both men and women, and hypertriglyceridemia in women." (PMID 26880028, 2016). "The association of the Klotho variant with the metabolic syndrome could be linked to its observed influence on high blood glucose, high blood pressure, insulin resistance, hypertriglyceridemia and endothelial function." (PMID 26880028, 2016). "Klotho deficiency has also been shown to be associated with endothelial dysfunction and vascular aging, with several reports highlighting lower circulating levels in patients with several chronic conditions including hypertension, cardiovascular disease (CVD) and Alzheimer disease." (PMID 35286490, 2022). "Despite convincing experimental evidence regarding the role of klotho deficiency in the pathogenesis of hypertension and salt hypertension, the roles of klotho in human blood pressure regulation and pathogenesis of hypertension remain largely unknown." (PMID 33504927, 2021). "Moreover, aging enhanced positive effects of the Klotho polymorphism on CAD combined with hypertension, indicating the possibility that the KLOTHO gene might play a part in the age-related occurrence of CAD combined with hypertension." (PMID 30547758, 2018).
Hypertension (continued). "Thus, Klotho deficiency may be a pathological factor for aging‐associated arterial stiffness and hypertension." (PMID 29659128, 2018). "In conclusion, Klotho C1818T variant may be associated with a decreased risk of hypertension." (PMID 30547758, 2018). "Secondary hyperaldosteronism promotes hypertension and oxidative stress and reduces Klotho protein production." (PMID 41373735, 2025). "Klotho has a broad impact on biological function, as Klotho supplementation or overexpression has been demonstrated to protect against hypertension, endothelial dysfunction, atherosclerosis, and vascular calcification." (PMID 40165603, 2025). "The observed reduction in Klotho is likely driven by oxidative stress and inflammatory cytokines, both of which are elevated in hypertension and under HFD conditions." (PMID 40869353, 2025). "Klotho levels are inversely associated with chronic diseases such as CKD, type 2 diabetes, hypertension, and ADRD, while preclinical Klotho therapy has been found to improve these conditions." (PMID 40574888, 2025). "Excess FGF23, in the context of low Klotho, can exert off-target effects, including direct stimulation of sodium reabsorption in the distal tubule, promoting volume expansion and hypertension." (PMID 41303567, 2025). "This connection was stronger in individuals over 60, males, and those with hypertension, highlighting folate’s role in regulating the anti-aging factor Klotho." (PMID 39040924, 2024). "The Klotho gene is an anti-aging gene discovered by Japanese scholar Kuro-o in 1997 while studying spontaneous hypertension." (PMID 38287280, 2024). "Klotho’s anti-inflammatory and antioxidant properties play a major role in several diseases, including nephrotic syndrome, hypertension, heart failure and lung carcinoma." (PMID 39091285, 2024). "Animal studies have demonstrated that enhancing Klotho expression can inhibit the progression of hypertension and mitigate kidney damage." (PMID 39329104, 2024). "Clinicians should consider monitoring Klotho levels as an early indicator of kidney health, particularly in patients with MetS and hypertension." (PMID 39777219, 2024). "AAV-mKlotho (murine Klotho) prevented the progression of spontaneous hypertension, eliminated renal tubule atrophy and dilatation, and attenuated kidney damage in rats with spontaneous hypertension." (PMID 38203812, 2024). "Klotho, a membrane-bound and soluble protein, has been found to modulate hypertension through physiological processes like vascular function and sodium balance." (PMID 39616409, 2024). "Our previous studies have confirmed that in the context of DKD, renal aging is accelerated, and factors such as hyperglycemia, inflammation, oxidative stress, and hypertension can induce the downregulation of klotho expression." (PMID 39558979, 2024). "Differences in serum Klotho quartiles were statistically significant with respect to sex, drinking status, hypertension, and glomerular filtration rate (P < 0.05)." (PMID 38769411, 2024). "According to statistical analysis, klotho levels were significantly reduced in patients with essential hypertension compared to the control (1.52 ± 0.87 vs. 2.45 ± 0.90, P < 0.001)." (PMID 39616409, 2024). "The major finding of the present study was klotho was significantly reduced in essential hypertension patients compared to controls." (PMID 39616409, 2024). "Considering the characteristics of the population with and without MALE during follow-up, we observed differences in male sex, hypertension, and Klotho and FGF23 baseline levels." (PMID 37061530, 2023). "We also conducted a subgroup analysis to further investigate the reciprocal relationship between serum Klotho protein concentration and hypertension for postmenopausal women." (PMID 37528365, 2023). "The Klotho protein has been recognized as a regulator of hypertension development through various pathways." (PMID 37528365, 2023).
Hypertension (continued). "After fully adjusting for potential confounders, a significant inverse relationship between serum Klotho concentration and hypertension was observed." (PMID 37528365, 2023). "Participants with lower quartile of serum Klotho concentration had a higher prevalence of hypertension than those in higher quartiles (Q1:62.29% vs. Q2: 48.52% vs. Q3: 47.33% vs. Q4: 55.02%, p < 0.001)." (PMID 37528365, 2023). "Logistic regression analysis showed that hypertension, BMI, Cr, Ca+2, PO-4 and VLDL were risk factors for cardiovascular complications, and Klotho level was a protective factor." (PMID 37492290, 2023). "Low levels of Klotho have been found in essential and in renovascular hypertension and they directly correlate with GFR, suggesting the involvement of Klotho in the pathogenesis of kidney injury in hypertensive disorders." (PMID 37298378, 2023). "After 65 months of follow-up in a large cohort of American patients with hypertension from the NHANES, low serum Klotho concentration was associated with increased all-cause mortality, but not cardiovascular mortality." (PMID 36457804, 2022). "With worsening CKD, klotho deficiency is becoming a status quo condition, as circulating klotho levels decline, arterial stiffness and hypertension ensue." (PMID 36304157, 2022). "Serum klotho levels showed a positive relationship with hypertension (beta coefficient: 17.371) and dyslipidemia (beta coefficient: 22.075) in individuals with hypertension or dyslipidemia." (PMID 36221064, 2022). "The effects of Klotho on the health and survival of patients with hypertension can be mediated in several ways." (PMID 36457804, 2022). "Collectively, the therapeutic activity of Klotho in patients with CVD (including hypertension) represents a fascinating and promising perspective for the future." (PMID 36457804, 2022). "SIRT1 and Klotho levels increase in pre-hypertensive patients before they decrease with the onset of hypertension and progression of the disease." (PMID 34670596, 2021). "An inverse relationship between circulating klotho and mean BP changes following salt loading was reported in patients with hypertension, suggesting that reduced levels of serum klotho contribute to salt-sensitive hypertension in the elderly." (PMID 33803946, 2021). "That is, we postulated that resistance exercise that led acute hypertension would decrease endothelial function, and the reduction in endothelial function would be related to Klotho's response." (PMID 34713986, 2021). "Correspondingly, Klotho deficiency in mice has been shown to accelerate and exacerbate HFD-induced arterial stiffening and hypertension, via down-regulation of vascular AMPKα expression, and activity." (PMID 32982966, 2020). "Hyperglycemia, inflammation, oxidative stress, and hypertension induce renal inherited cellular senescence and the downregulation of antiaging proteins, such as Sirt1 and Klotho, and the inactivation of the lysosome-dependent autophagy pathway." (PMID 32774664, 2020). "In light of the proven crosstalk between SIRT1 and AMPKα activity, SIRT1 activation can be a potential medical target to improve arterial stiffness and hypertension due to Klotho repression." (PMID 33117155, 2020). "The expression of Klotho declines with advancing age partly elucidating the high prevalence of arterial hypertension in the elderly population." (PMID 33117155, 2020). "Age, arterial hypertension, median acPWV, and Klotho were selected in univariate Cox regression analysis as predictors of mortality." (PMID 32872092, 2020). "Patients in the low-Klotho group had more commonly hypertension (p = 0.038), and higher values of ccIMT (0.86 ± 0.16 vs 0.79 ± 0.15, p = 0.034) compared with those in the high-Klotho group." (PMID 31185930, 2019). "It was reported that at age of 70 years, the serum level of Klotho is only about one half of what it was at age of 40 years, while the prevalence of arterial stiffness and hypertension is increased in the aged population." (PMID 29659128, 2018).